ROR1 (ROR family WNT receptor 1)
Diseases named in the same sentence as ROR1 in open-access papers (continued):
Sharing a sentence is not in itself a finding about the gene and the disease.
cancer (161 papers, 2010 to 2026). A tumor composed of atypical neoplastic, often pleomorphic cells that invade other tissues. "As proof of concept, the CAR T‐cells used in this study are directed against ROR1, a cancer‐associated receptor typically expressed in intestinal adenocarcinomas." (PMID 40249196, 2025). "In this manner, ROR1 is a compelling candidate due to its association with poor clinical outcomes, role in maintaining cancer stemness (Section 4), and low expression in normal tissues." (PMID 40869147, 2025). "One emerging cancer-associated target is Receptor tyrosine kinase like Orphan Receptor 1 (ROR1), which is an oncofetal RTK-like protein that is highly expressed in embryogenesis and minimally expressed in developed tissue." (PMID 39000112, 2024). "All of these findings point to an association between the expression of the lncRNA DLEU2 and ROR1 and CSCs in BC tumors and these associations possibly drive cancer cells toward chemoresistance." (PMID 38296962, 2024). "Examples of potentially anti-proliferative pathways activated by paracrine signalling include those involving ACVR1C, MAP3K14 and ROR1, linked to inhibition of cancer growth including in the context of CCA." (PMID 39492622, 2024). "In CLL the del (13q) results in the loss of miRNA-15a and miRNA-16-1, leading to increased ROR1 expression and promoting cancer cell survival by overexpressing BCL-2." (PMID 39551787, 2024). "Several studies have reported that high ROR1 expression is significantly associated with cancer survival." (PMID 37241228, 2023). "Although Ror1 has been implicated in the progression of various types of cancer, only a few reports have suggested an involvement between Rif and cancer progression." (PMID 37703992, 2023). "This study revealed that ROR1 expression was significantly associated with poor prognosis in various cancer types." (PMID 36557069, 2022). "This meta-analysis revealed that ROR1 expression is associated with poor survival in patients with various cancers." (PMID 36557069, 2022). "Focusing on the roles of CS in regulating cancer hallmark capabilities, we show here the involvement of ROR1, known as a receptor for WNT5A, in CS-E-mediated upregulation of invasion activity in MDA-MB-231 cells." (PMID 35712490, 2022). "Together, aberrant expression of ROR1 and associated pro-growth signaling events are observed in many types of malignancies, making ROR1 an attractive therapeutic target for anti-cancer drug development." (PMID 34123850, 2021). "ROR1 expression has also been associated with cancer stem-like cells (CSCs) as well as those with metastatic potential, and its inhibition has been shown to decrease stem cell markers in CLL7,14,34." (PMID 34088900, 2021). "As Ror1 has been implicated to be a potential target for cancer therapy, we selected this protein for further investigation." (PMID 28432357, 2017). "An increasing number of studies indicated that ROR1 is highly associated with human cancers; however, the biological function of ROR1 remains to be assessed." (PMID 26576539, 2015). "The SNP is located in a cancer-specific enhancer situated ~60 kb upstream of the cancer-associated ROR1 gene, which is one of the potential target genes located in the TAD containing the candidate SNP." (PMID 24920305, 2014). "Lastly, ROR1 signaling has been implicated in cell survival and migration in cancer cells." (PMID 39816690, 2025). "High ROR1 gene expression in the I-SPY2 transcriptomic dataset was associated with worse event-free survival in hormone receptor (HR)+/HER2− patients with high residual cancer burden after neoadjuvant treatment." (PMID 38408999, 2024). "They interrogated a Bioinformatic database, which included the Genotype-Tissue Expression (GTEx) Portal and the 33 datasets from the Cancer Genome Atlas (TCGA), and identified variant truncated isoforms of ROR1 that were also expressed in some normal and neoplastic cells." (PMID 39062146, 2024).
cancer (continued). "The aggressive behavior of various human cancers has been linked to the upregulation of ROR1." (PMID 37469704, 2023). "When assessed in the context of residual disease, high-level expression of ROR1 associated with a significantly worse outcome for patients with HR + HER2- tumors who had a high post-treatment residual cancer burden (RCB-II/III) (HR = 1.41, 95% CI = 1.11–1.80, LRp = 0.01)." (PMID 37029329, 2023). "Moreover, OC tumors with high ROR1 levels were enriched for the expression signature of genes associated with cancer stem cells and EMT, which facilitates cancer cell migration, metastatic development, and drug resistance." (PMID 37400436, 2023). "As both YAP/TAZ and BMI-1 regulate the differentiation and self-renewing capacity of cancer stem cells, these observations could provide the molecular basis underlying the ROR1-associated stemness phenotype." (PMID 33445713, 2021). "Importantly, to better understand if ROR1 has any association with metastatic behavior of cancer cells, we used a panel of six HCC cell lines with well-established EMT status." (PMID 30832318, 2019). "Among the ROR family, the association of ROR1 with cancer was first shown in B-cell malignancies." (PMID 30832318, 2019). "Interestingly, aberrant YAP/TAZ expression has been linked to drug resistance in several cancers, underlining a common feature with ROR1 and raising the possibility that ROR1 and YAP/TAZ signaling reinforce each other to make cancer cells treatment resistant." (PMID 31382410, 2019). "Finally, investigating the potential of ROR1 as a diagnostic or prognostic biomarker in cancer could help identify patients who are most likely to benefit from ROR1-targeted therapies." (PMID 40869147, 2025). "We report novel functional significance for a transcript variant of ROR1 that lacks an SP for cell surface localisation, raising important questions about the mechanism of action of a gene widely considered druggable because of its cell surface localisation in cancer tissues." (PMID 36289823, 2022). "In addition, EMT-related microRNAs were noted, including miR-218-2, which was frequently repressed and co-methylated with its host gene SLIT3; miR-214, which targets EZH2, β-catenin, and BIRC7 —all were genes implicated in cancer metastasis and invasion; miR-382, which targets ROR1." (PMID 30922328, 2019). "Indeed, ROR1-positive carcinomas were associated with aggressive disease progression and lower rates of progression-free survival or overall survival rates of patients, as well as treatment resistance, suggesting a high potential for ROR1-targeted therapies during advanced disease stages." (PMID 31382410, 2019). "This widespread upregulation of ROR1 across diverse malignancies points towards an important oncogenic role in cancer development and progression and provides insight into its potential as a relevant therapeutic target." (PMID 40869147, 2025). "In certain cancer types, including BC, high receptor tyrosine kinase-like orphan receptor 1 (ROR1) expression levels have been reported, making it an interesting target for immunotherapies such as CAR-T cell therapy." (PMID 40675157, 2025). "In various cancer types ROR1 expression has been described to stimulate EMT which facilitates metastasis formation." (PMID 41355329, 2025). "Receptor tyrosine kinase-like orphan receptor 1 (ROR1) is a key regulator of cancer stem cell (CSC) biology and signaling." (PMID 40869147, 2025). "This differential expression profile makes ROR1 a promising target for cancer therapy, potentially allowing for selective targeting of malignant cells while minimizing damage to healthy tissues." (PMID 40869147, 2025). "Cancers expressing high levels of ROR1 exhibit aggressive growth and migration that correlates with poor patient prognosis." (PMID 40667148, 2025). "The specific roles of ROR1 in cancer can vary depending on the cancer type and the cellular context." (PMID 40869147, 2025).
cancer (continued). "The importance of ROR1 in CSCs has been observed across multiple cancer types, indicating its involvement in the fundamental characteristics of these cells, such as self-renewal and drug resistance." (PMID 40869147, 2025). "The uniform expression of ROR1 in cancer, along with its internalization capability and strong correlation with BRD4, makes it a promising target for conjugation." (PMID 39816690, 2025). "ROR1 represents a promising target for the development of novel antiproliferative compounds, giving its high expression in different cancer cell lines." (PMID 40328670, 2025). "While minimally expressed after embryogenesis, ROR1 is aberrantly upregulated in numerous cancers, including ovarian, breast, pancreatic, and hematologic malignancies." (PMID 40869147, 2025). "The binding of 22.0405 to ROR1 was also confirmed using human cancer cells that endogenously express ROR1, such as the MCL cell line JeKo-1." (PMID 41479906, 2025). "Therapeutic regimens that combine ROR1-targeted agents with other anti-cancer treatments are also being investigated." (PMID 40869147, 2025). "Receptor tyrosine kinase-like orphan receptor 1 (ROR1), a tumor-associated antigen (TAA), is widely expressed in various cancers." (PMID 40723210, 2025). "Receptor tyrosine kinase-like orphan receptor 1 (ROR1), which is overexpressed in malignant tumors but minimally expressed in normal tissues, presents a promising target for immunotherapy." (PMID 40723210, 2025). "On the other hand, ROR1 exhibits aberrant expression in a wide spectrum of human cancers, including both hematological malignancies and solid tumors, and it is frequently associated with aggressive disease states and poor clinical outcomes." (PMID 40869147, 2025). "A US phase 1 trial (NCT02706392) aimed to treat patients with ROR1+ cancers, including TNBC, with CAR-T cells." (PMID 40675157, 2025). "Continued clinical trials evaluating the efficacy and safety of ROR1-targeted therapies in various cancers are essential to translate preclinical promise into clinical benefit." (PMID 40869147, 2025). "Receptor tyrosine kinase-like orphan receptor 1 (ROR1) is a transmembrane protein with low expression in healthy tissue but is highly expressed in embryonic development and cancer." (PMID 40427627, 2025). "Clinical trials evaluating the combination of BTK or BCL-2 inhibitors with ROR1-targeting therapies have yielded encouraging results, further underscoring the critical role of ROR1 in cancer progression and therapy resistance." (PMID 41479906, 2025). "The inhibition of ROR1, through diverse treatment modalities, has emerged as a clinically promising modality across multiple cancers." (PMID 40869147, 2025). "Chimeric antigen receptor (CAR) T‐cell therapy represents a promising approach for cancer treatment, with receptor tyrosine kinase‐like orphan receptor 1 (ROR1) emerging as a novel target in malignancies." (PMID 40249196, 2025). "The identification of ROR1 dimers and oligomers represent a new potential therapeutic target for cancer." (PMID 40667148, 2025). "ROR1 has emerged as a promising target in cancer immunotherapy because of its restricted expression in normal adult tissues and its overexpression in various malignancies." (PMID 39849645, 2025). "ROR1 has emerged as a critical player in cancer biology, and its expression has recently been shown to be essential in CSC signaling." (PMID 40869147, 2025). "Preclinical studies suggest that combining ROR1-targeted therapies with inhibitors of other oncogenic pathways can be more effective in eradicating drug-resistant cancer cells compared to single-agent treatments." (PMID 40869147, 2025). "This expression frequency is comparable to that reported in hematologic cancers, further supporting the rationale for targeting ROR1 in cancer immunotherapy with minimal immune-related adverse effects." (PMID 40723210, 2025).
cancer (continued). "Previous studies have shown that ROR1 contributes to cancer cell proliferation, migration, and angiogenesis." (PMID 40723210, 2025). "The identification of ROR1 dimers and oligomers represents a new potential therapeutic target for cancer." (PMID 41349767, 2025). "Within the network of non-canonical WNT signaling, the receptor tyrosine kinase-like orphan receptor 1 (ROR1) has garnered increasing attention due to its restricted expression pattern in normal tissue and its involvement in aggressive cancer phenotypes." (PMID 40869147, 2025). "It functions as a substrate for ROR-1, and its activation through phosphorylation events mediated by ROR-1 can significantly influence the behavior of cancer cells." (PMID 41477115, 2025). "These aspects highlight the importance of STAT3 in maintaining the survival of certain cancer cells through the ROR1-Wnt5a axis." (PMID 39551787, 2024). "We conclude that the detection of ROR1 protein in various cancers cannot be ascribed to the expression of ROR1v3." (PMID 39062146, 2024). "Receptor tyrosine kinase-like orphan receptor 1 (ROR1) is a developmentally restricted type I glycoprotein expressed by a variety of different cancers." (PMID 39062146, 2024). "Given that ROR1 signaling actively contributes to the maintenance, self-renewal, and chemoresistance of cancer cells, this raises the possibility that there is a link between ROR1 and the lncRNA DLEU2 pathway and that this pathway regulates CSC behavior." (PMID 38296962, 2024). "Among the two ROR proteins (ROR1 and ROR2), prior studies found that BC with high levels of ROR1 is associated with cancer stemness and EMT, rapid disease progression after chemotherapy, and short survival." (PMID 38296962, 2024). "Targeted anti-ROR1 therapy is considered a promising strategy for treating cancer because ROR1 is frequently overexpressed on the surface of cancer cells and is associated with tumorigenesis and drug resistance." (PMID 39551787, 2024). "These approaches represent potential new immunotherapies for targeting ROR1 in hematological malignancies, expanding treatment options for patients with severe diseases and poor outcomes." (PMID 39551787, 2024). "Cirmtuzumab, which targets the interaction between ROR1 and Wnt signaling, inhibits Wnt5a-mediated signaling by binding to ROR1, reducing cancer cell proliferation and survival." (PMID 39518123, 2024). "Silencing ROR1 represses the expression of EMT-related genes and impairs cancer cells’ migration and invasion as well as their metastatic abilities, suggesting the stemness-inducing role of ROR1 in BC cells." (PMID 38296962, 2024). "Results indicate that ROR1 protein levels were elevated in the highly aggressive ARneg-AI PC3 cancer cell line." (PMID 39000112, 2024). "Some of these approaches have been evaluated in clinical trials, indicating the potential of targeting ROR1 in cancer treatment." (PMID 39551787, 2024). "The detection of soluble ROR1 in PF allows to distinguish NC from cancer patients (NC vs. PDAC (PER-), p = 0.0012; NC vs. PDAC (PER+), p = 0.0011), but not to differentiate PDAC (PER-) from PDAC (PER+)." (PMID 38846943, 2024). "Our lab has previously investigated the anti-cancer effects of ROR1 inhibitor strictinin, which is a naturally derived compound that is very structurally similar to PGG." (PMID 39000112, 2024). "This study identifies pentagalloyl glucose (PGG), for the first time, as an ROR1 inhibitor that targets ROR1-expressing PC3 cancer cells in vitro." (PMID 39000112, 2024). "Epithelial-mesenchymal transition, which explains cancer invasion, metastasis, and progression, was found to be mediated by mediators such as ROR1." (PMID 37779899, 2023). "Many studies have shown that ROR1 was highly expressed in several malignant cells, and the actual function of ROR1 in cancer was in search." (PMID 37241228, 2023). "In summary, our results provide evidence that ROR1 increases cell proliferation and cancer cell metastatic ability." (PMID 37241228, 2023).
cancer (continued). "Previous studies have shown that inhibiting ROR1 effectively mitigates aggressive cancer phenotypes." (PMID 38213538, 2023). "Our results show that ROR1 and its downstream STAT3 are co-expressed in epithelial as well as stromal cells of OC tumors, including cancer-associated fibroblasts or CAFs." (PMID 37400436, 2023). "Although Ror1 and Ror2 play important roles during embryonic development, their upregulated expression contributes to cancer progression by regulating the proliferation, migration, invasion, survival, and chemoresistance of cancer cells." (PMID 37703992, 2023). "The selective expression of ROR1, mainly attributed to malignant cells, has made this receptor an attractive target for cancer therapy to avoid off-target cytotoxic effects." (PMID 37400436, 2023). "In agreement with this view, preclinical and clinical trials investigating ROR1 as a drug target are emerging as relevant anti-cancer approaches." (PMID 37237541, 2023). "New cancer treatments have emerged that target ROR1, such as monoclonal antibodies (mAbs), anti-body-drug conjugates (ADCs), or chimeric antigen receptor (CAR)-T cells." (PMID 37241228, 2023). "In a study that detected ROR1 + cancer cells in buffy coat blood samples, the linearity of aggregation did not increase with cell concentration." (PMID 37161039, 2023). "al. developed a dual-layer paper microfluidic chip as an alternative to detect ROR1+ (receptor tyrosine-like orphan receptor one) cancer cells from the undiluted and untreated buffy coat blood samples." (PMID 36979600, 2023). "We selected ROR1 as the molecular target of our experiments because ROR1 is a TAA expressed in a wide variety of cancers; therefore, any optimization derived from our work will have a broad range of applications." (PMID 37719008, 2023). "ROR1 can contribute to the β-catenin-independent Wnt pathway to activate cancer cell growth by binding to the Wnt5a ligand." (PMID 37241228, 2023). "ROR1 is involved in sustaining the self-renewal of cancer stem cells, and is related to disease activity and resistance to chemotherapy." (PMID 37111634, 2023). "ATL II decreased the proliferation and viability of human colorectal cancer cells by disrupting the LncRNA XIST/miR-30a-5p/ROR1 signaling pathway, reducing cancer cells’ chemosensitivity and improving the efficacy of chemotherapy." (PMID 37241729, 2023). "ROR1 is a type I transmembrane protein, that expresses during cancer and embryonic development and, has been identified as an oncofetal protein." (PMID 37469704, 2023). "KAN 0439834 is a specific small molecule ROR1 inhibitor which has been reported to retain cytotoxic effects against ROR1-expressing cancer cells." (PMID 37237541, 2023). "In this study, ROR1 was shown to promote the ability of cancer cells to migrate in Matrigel, engraft in immunodeficient mice, and survive chemotherapy." (PMID 36873868, 2023). "High-level expression of ROR1 was highest in HR- HER2- subtype and was associated with worse EFS in HR + HER2- patients with high post-treatment residual cancer burden (RCB-II/III)." (PMID 37029329, 2023). "The NCT02706392 trial conducted by the Fred Hutchinson Cancer Center was a Phase I trial intended to treat patients with ROR1+ cancers." (PMID 36873868, 2023). "We further tested a list of cancer cell lines that express the ROR1 antigen and with a GFP reporter marker." (PMID 35892876, 2022). "Due to its unique expression in tumors, ROR1 has been recognized as an interesting target for cancer treatment." (PMID 36297673, 2022). "These fusion proteins represent a promising and novel anticancer active immunotherapy strategy for targeting ROR1 expressing human cancers." (PMID 36497309, 2022). "ROR1 is considered an ideal druggable target for oncology because of demonstrated pro-tumourigenic actions, cancer-specific expression, cell surface expression and availability of drugs that can regulate ROR1 action." (PMID 36289823, 2022).